PMS2 (PMS1 homolog 2, mismatch repair system component)
Diseases named in the same sentence as PMS2 in open-access papers (continued):
Sharing a sentence is not in itself a finding about the gene and the disease.
tumor (continued). "Her cecal carcinoma was immunohistochemically stained and also showed isolated PMS2 expression loss in the neoplastic cells but not in tumor-infiltrating immune cells." (PMID 36291559, 2022). "Colorectal cancers with MLH1/PMS2 mutations had higher TMB than endometrial cancer and other tumor histologies, showing that the TMB count is widely variable according to both type of MMR defect and tumor site origin." (PMID 36291761, 2022). "MMR IHC of the primary tumor showed the loss of MLH1 and PMS2 expressions." (PMID 35457245, 2022). "In addition, using BRAF V600E IHC and/or BRAF molecular analysis, we found that the three tumours with dMMR (MLH1 & PMS2) were BRAF wild-type." (PMID 35768447, 2022). "In this particular case MLH1 and PMS2 expression was lost at all tumor sites." (PMID 36128324, 2022). "In conclusion, this thorough molecular characterization of a single patient with multiple tumor lesions unveiled the co-occurrence of germline POLE and PMS2 pathogenic variants (from the maternal and paternal lineage, respectively) predisposing to the development of multiple neoplasms." (PMID 35260767, 2022). "Our results show that PMS2 mutations often occur simultaneously with NF1 mutations, which may indicate the dedifferentiation tendency and high mutation load of this group of tumor cells." (PMID 35865459, 2022). "Taking into account the important relationship between the MMR pathway and tumor behavior, the aim of this study was to assess the influence of the PMS2 protein on the prognosis of patients with OSCC as well as to correlate these findings with clinical-pathological aspects." (PMID 33247565, 2021). "She had been categorized as “screen-negative” by our model based on MLH1/PMS2 protein deficiency in her tumour and presence of MLH1 promoter methylation." (PMID 33467402, 2021).
tumor (continued). "Again, the MMR defective signature was concordant with the MLH1-/PMS2- tumor status in SPS." (PMID 33672345, 2021). "One tumor showed MSI with selective loss of MLH1 and PMS2 (1.9%)." (PMID 34367937, 2021). "The one patient who had absence of MLH1/PMS2, had follow-up braf testing consistent with sporadic tumor and did not have any variant identified on comprehensive (47-gene panel) germline testing." (PMID 33436027, 2021). "NGS analysis of these tumours identified PMS2 mutations (R134* germline mutation in one tumour and M1R and c.1239delA somatic mutation in the other) as the primary event and somatic MSH6 mutation (c.3261dupC) as the secondary event in both tumours." (PMID 32664968, 2020). "In addition to these two more common pattern of MMR protein expression in tumour with MMRD, other less frequent patterns, such as isolated losses of PMS2 and MSH6 also occurred in LS patients due to germline mutations of PMS2 and MSH6, respectively." (PMID 32664968, 2020). "When MSI-H and lack of expression of both MLH1 and PMS2 are observed, tumor BRAF V600E mutation and/or MLH1 promoter hypermethylation testing is recommended to distinguish sporadic colorectal cancer from CRC caused by an MMR defective system." (PMID 33027913, 2020). "Even though we have not detected a PV in PMS2 gene, the IHC staining of proband’s tumor tissue showed an isolated loss of the PMS2 protein, but not MLH1—as expected." (PMID 32197529, 2020). "MSH6 and PMS2 are both considered to be tumor-suppressor and mismatch repair (MMR) genes." (PMID 32508881, 2020). "Black patients with MSI tumours occurred in younger patients with left- (36%) and right-sided (59%) tumours, associated with dMSH2/6 (45%), and dMLH1/PMS2 (36%) tumours with a lack of BRAF mutations, indicating a possible LS cause." (PMID 31636305, 2019). "In FFPE CRC tissue, the amount of Fn DNA was associated with proximal tumor location (p = 0.009), MSI-positive (p < 0.0001), BRAF mutated tumors (p = 0.002), and the loss of expression of mismatch-repair proteins MLH1 (p < 0.0001) and PMS2 (p < 0.0001)." (PMID 31555583, 2019).
tumor (continued). "Similar to previous reports, MGMT was methylated and multiple DNA MMR genes (MLH1 and PMS2) were mutated in the recurrent tumor, but these variants were not present at diagnosis." (PMID 29487696, 2018). "Investigating MMR gene mutations and methylation status in MSI tumor samples, we only observed few cases of MSH6 (MutSα), MSH3 (MutSβ), PMS2 (MutLα), PMS1 (MutLβ), and MLH3 (MutLγ) high-impact mutations often in combination with inactivation of other MMR genes." (PMID 29636374, 2018). "Regarding the missense variant (MLH1 c.2050T>G), it was present in a patient whose tumor was MSI with absence of MLH1/PMS2." (PMID 30256826, 2018). "In two PMS2 p.Pro246Cysfs*3 cases with strong stains ColoSeq did not detect a second tumour mutation so these patients developed a sporadic CRC unrelated to their germline mutation." (PMID 28466842, 2017). "Moreover, three cases with complete loss of MLH1 and PMS2 expression in all three tumour blocks also displayed subclonal loss of MSH6 expression (10%, 20% and 90% of the tumour respectively) in one tumour block." (PMID 28424422, 2017). "If tumor is MLH1/PMS2-deficient and somatic BRAF mutation is not detected or MLH1 promoter methylation is not identified, this MSI-H is less likely to be sporadic, and testing for germline mutations is indicated." (PMID 28699072, 2017). "Thus, PMS2 plays a tumor suppressor role in PCa cells and this effect is substantiated by enhanced proliferation due to silencing of this gene as observed in normal PWR-1E cells." (PMID 26036629, 2015). "In sum, IHC was performed on 24 tumours, and 21/24 (87.5%) showed expression of PMS2." (PMID 24790682, 2014). "However, whereas 90% of tumours in mutation carriers were MSI-high or MSI-low, only 12.5% of tumours showed abnormal staining of PMS2 by IHC." (PMID 24790682, 2014). "In addition, inhibition of apoptosis via the Bcl-2 pathway, and the down-regulation of PMS2 and topoisomerase 11 DNA mismatch repair proteins have been proposed as mechanisms that desensitize tumor cells in spheroids to antitumor agents." (PMID 24146752, 2013). "Evaluating the expression of MLH1 and PMS2 in GBM may therefore provide a useful index for predicting the efficiency of TMZ anti-tumour activity." (PMID 24259277, 2013). "In addition, a significant reduction in MLH1 and PMS2 expression was observed in recurrent GBM tumours during TMZ administration." (PMID 24259277, 2013).
tumor (continued). "Furthermore, ECM components, such as collagen isoforms, Fibrillin-1, EMILIN-1, Prolargin, and Lumican, were found to be highly expressed in the MLH1/PMS2-deficient tumor area, suggesting a connection between DNA repair deficiencies, ECM remodeling, and tumor progression." (PMID 40076915, 2025). "PMS2 (Postmeiotic Segregation Increased 2) is a crucial component of the DNA mismatch repair (MMR) system, and its loss of expression is often indicative of microsatellite instability (MSI), which plays a significant role in tumor development and treatment response." (PMID 40519284, 2025). "However, for MSH6 and PMS2 carriers, starting later and extending the intervals between screenings may be more effective considering the balance between cost and timely tumor detection." (PMID 39457591, 2024). "Interestingly, PMS2 expression loss was also observed in adjacent non-neoplastic epithelia but not in tumor-infiltrating immune cells." (PMID 36291559, 2022). "Of note, zonal heterogeneity of the staining with areas of the tumor showing an abrupt loss of MLH1 and PMS2 protein expression may be an indicator of acquired inactivating alterations of MLH1 (primarily, MLH1 promoter hypermethylation), arguing for sporadic cancer rather than LS-related cancer." (PMID 33530449, 2021). "It is worth noting that MSI tumor HC8T lacked PMS2 staining and had heterozygous R563X mutation." (PMID 30680068, 2018). "Thus, we conclude that PMS2 plays a tumor suppressor role by enhancing apoptosis in PCa cells." (PMID 26036629, 2015). "Thus, the low sensitivity of IHC to detect tumours caused by the PMS2 splice mutation is in keeping with a non-functional protein located at the right place in the cell detectable by IHC." (PMID 24790682, 2014).
tumor (continued). "Furthermore, staining for MLH1 and PMS2 was positive for all the tumours." (PMID 19527492, 2009). "When PMS2 is present in both tumor and stromal cells, it suggests that the MMR system remains intact, and the tumor is likely microsatellite stable (MSS)." (PMID 40519284, 2025). "The immunohistochemical analysis of MMR genes revealed two distinct tumor areas, separated by a clear topographic boundary, with the heterogeneous expression of MLH1 and PMS2 proteins." (PMID 40076915, 2025). "A significant expression of PMS2 was noted with PNI, LVI, tumor type, grade, T and N-stage, mucinous differentiation, and ITL." (PMID 37664303, 2023).